FGF9 (fibroblast growth factor 9)
Diseases named in the same sentence as FGF9 in open-access papers (continued):
Sharing a sentence is not in itself a finding about the gene and the disease.
hepatocellular carcinoma (continued). "To conclude, these data together provide evidence that the FGF9 effects on hepatoma/hepatocarcinoma cells may be mediated mainly by FGFR3‐IIIb/IIIc." (PMID 32378800, 2020). "Interestingly, it has been shown that miR-140-5p targets FGF9 to inhibit hepatocellular carcinoma growth and metastasis." (PMID 33234721, 2020). "Knockdown FGF9 via siRNA (small interfering RNA) resulted in a similar phenotype as ectopic miR-140-5p expression, whereas FGF9 overexpression reversed the effects of miR-140-5p in hepatocellular carcinoma growth and metastasis." (PMID 33234721, 2020). "In response to FGF9, FGFR3‐IIIb overexpressing hepatoma/hepatocarcinoma cell lines formed even larger clones than the vector controls, while FGF9‐treated cells with overexpressed FGFR3‐IIIc showed an elevated migratory phenotype, as indicated by the wound‐healing and transwell assay." (PMID 32378800, 2020). "We next examined the effect of FGF9 on hepatoma cell line HepG2 cells." (PMID 31862949, 2019). "When compared to other FGFR3‐IIIb/IIIc ligands, FGF9 is the most efficient growth factor under our conditions and may act not only on human hepatoma/hepatocarcinoma cell lines but also on unaltered hepatocytes as well as on early stages of hepatocarcinogenesis." (PMID 32378800, 2020). "miR-140-5p also plays a tumor suppressor role in hepatocellular carcinoma by controlling NF-κB activity by directly regulating DNMT1 expression, and suppresses tumor growth and metastasis by targeting TGFBR1 and FGF9." (PMID 27588393, 2016). "FGF8 and FGF10 are involved in embryonic liver development, FGF7 and FGF9 in repair in response to liver injury, and FGF5, FGF8, FGF9, FGF17, and FGF18 in the development and progression of hepatocellular carcinoma." (PMID 27148532, 2016). "In addition, FGF5, FGF8, FGF9, FGF17, and FGF18 play roles as paracrine signals in the development and progression of hepatocellular carcinoma." (PMID 27148532, 2016). "FGF9 induces non‐alcoholic steatohepatitis (NASH) to develop into severe fibrosis and eventually lead to hepatocellular carcinoma (HCC) by promoting extracellular matrix (ECM) accumulation." (PMID 37566761, 2023). "Nevertheless, FGF9 elicited proliferation of hepatoma/hepatocarcinoma cells independent of their FGFR3‐splice variant profile, which could be blocked by knockdown of FGFR3 and not of the other FGFRs." (PMID 32378800, 2020).
prostate carcinoma (18 papers, 2005 to 2025). A carcinoma that arises from epithelial cells of the prostate gland. "The findings in this study revealed that enhanced expression of Cx3cr1 after Klf5KR knockin in Pten-deficient prostate cancer is an endogenous molecular mechanism by which FGFR1 signaling is activated by its paracrine ligand FGF9." (PMID 38781024, 2024). "The overactivated FGFR1 signaling in Ac-Klf5–deficient and Pten-null prostate cancers can be attributed at least partly to the increased expression of FGF9." (PMID 38781024, 2024). "Coculturing of CAFs with prostate cancer PC-3 and DU 145 cells with the KLF5KR mutant released more Fgf9 than did the WT control at both the mRNA and protein levels, indicating that the signal from prostate cancer cells was essential for CAFs to release FGF9." (PMID 38781024, 2024). "Increased FGF9 and upregulated CX3CR1 cooperate to activate FGFR1 signaling, which leads to the progression of PTEN-deficient prostate cancer." (PMID 38781024, 2024). "Deacetylation of KLF5 in prostate cancer cells stimulated inflammatory cancer-associated fibroblasts (iCAFs) through TNF-α to release FGF9, which in turn activated FGFR1 signaling in prostate cancer cells." (PMID 38781024, 2024). "Upregulation of FGF9 and CX3CR1 is associated with FGFR1 activation in Pten-deficient human prostate cancer." (PMID 38781024, 2024). "FGF9 activated FGFR1 signaling in a dose-dependent manner within 15 minutes in DU 145 prostate cancer cells, as indicated by the phosphorylation of ERK and FRS2." (PMID 38781024, 2024). "CX3CR1 inhibition blocked FGFR1 activation triggered by FGF9 and sensitized PTEN-deficient prostate cancer to the AKT inhibitor capivasertib." (PMID 38781024, 2024). "Collectively, FGF9 and CX3CR1 depended on each other to activate FGFR1 in PTEN-deficient prostate cancer." (PMID 38781024, 2024). "LIM domain only 2 (LMO2) was put forward as a new marker in prostate cancer, which increases the viability of prostate cancer cells via releasing FGF-9 and IL-11 from prostate fibroblasts." (PMID 36865499, 2023). "Positive FGF9 immunostaining in prostate cancer cells was recorded in all (100%) cases of bone metastasis as compared to 43% in primary tumors derived from human organ-confined prostate cancer." (PMID 31137764, 2019). "Several studies displayed that FGF9 is a key mediator of tumor progression in many human cancers, including lung adenocarcinoma, prostate cancer, and HCC." (PMID 30646925, 2019). "The role of FGF9 and AR in the mechanism of prostate cancer pathogenesis, in view of its resistance to castration, has been investigated." (PMID 31137764, 2019). "FGF9 induced osteoblast proliferation and new bone formation in human AR-negative prostate cancer xenografts which overexpressed FGF9 relative to other bone-derived prostate cancer cells." (PMID 31137764, 2019). "As an example, MSCs undergo osteoblastogenesis due to the secretion of Fibroblast Growth Factor 9 (FGF9) by bone metastatic prostate cancer 3 (PC-3) carcinoma cells, which results in the osteopetrotic phenotype of MSCs in prostate cancer." (PMID 28473858, 2017). "Overexpressing FGF9 can promote the formation of reactive stroma and initiation in prostate cancer cells." (PMID 27166269, 2016). "We further focused on p-AKT+ samples to determine whether FGF9 is an active ligand of FGFR1 and whether CX3CR1 is required for FGFR1 activation in PTEN-deficient prostate cancer." (PMID 38781024, 2024). "Notably, FGF9 and CX3CR1 depended on each other to activate FGFR1 in PTEN-deficient human prostate cancer." (PMID 38781024, 2024). "We therefore further evaluated whether FGF9 and CX3CR1 are associated with FGFR1 activation in PTEN-deficient human prostate cancer." (PMID 38781024, 2024).
prostate carcinoma (continued). "The miRNA 183/182 cluster, which was downregulated in our series, has also been found to be deregulated in medulloblastoma and prostate cancer, and the cluster has been shown to inhibit cell proliferation and migration by targeting FGF9 and NTM in Schwann cells." (PMID 23776562, 2013). "Of particular interest are: FGF9 which may stimulate the growth of prostate cancer, brain cancer and endometrium; and IER3 (IEX-1), PHLDA2 (TSS3), IAPP (amylin), and SST, all of which may play roles in apoptosis." (PMID 15691381, 2005). "Interruption of Klf5 acetylation in Pten-deficient prostate cancer cells signaled iCAFs through TNF-α to promote FGF9 release, which in turn activated FGFR1 signaling in prostate cancer cells." (PMID 38781024, 2024). "The positive correlation between FGF9 and p-FRS2 reached significance in CX3CR1hi prostate cancer samples and disappeared in CX3CR1lo samples." (PMID 38781024, 2024). "Collectively, FGF9 was a ligand of FGFR1 that was mainly released by CAFs and activated FGFR1 signaling in prostate cancer." (PMID 38781024, 2024). "In patients with prostate cancer, high expression levels of CX3CR1 were required for FGF9 to activate FGFR1 signaling, and CX3CR1 was positively associated with FGFR1 activation under FGF9 secretion." (PMID 38781024, 2024). "Interruption of Klf5 acetylation, on the one hand, signals iCAFs to release FGF9 via TNF-α; on the other hand, deacetylation of Klf5 induces CX3CR1 expression in prostate cancer cells." (PMID 38781024, 2024). "In prostate cancer, FGFR1 and FGFR4 as well as the ligands FGF-1, FGF-2, FGF-6, FGF-8, FGF-9, and FGF-17 are all known to be over-expressed." (PMID 22078327, 2011). "Furthermore, in human prostate cancer tissue assays, we detected p-AKT, FGF9, CX3CR1, and p-FRS2 with IHC staining." (PMID 38781024, 2024). "We also tested the activation effects of FGF9 on FGFR1 signaling in prostate cancer cells with or without the KLF5KR mutant." (PMID 38781024, 2024).
ovarian carcinoma (15 papers, 2015 to 2026). A malignant neoplasm originating from the surface ovarian epithelium. "Abnormally produced FGF9 was associated with immunological markers, such as immunoinhibitory and chemokine receptors in ovarian cancer." (PMID 39071494, 2024). "Indeed, FGF9 signaling has been associated with the lethality of ovarian cancer through the control of metabolic reprogramming and downstream increase in metastatic potential." (PMID 41131959, 2026). "In this paper, we would explore the underlying mechanisms of FGF9 in ovarian cancer." (PMID 35190498, 2022). "Through comprehensive bioinformatic analysis, the expression level of FGF9 was discovered to be downregulated in ovarian cancer tissues." (PMID 35190498, 2022). "Later, further studies found that fgf9 not only plays an important role in ovarian cancer and bone development but also plays a very important role in mammal sex determination and differentiation." (PMID 36203875, 2022). "It has been reported that FGF9 is able to induce ovarian cancer cell invasion by activating the VEGF-A/VEGFR2 pathway." (PMID 35562985, 2022). "Then, we downloaded the statistics of TCGA-OV database and analyzed the effects of FGF9 expression on immune regulation of ovarian cancer patients via ssGSEA." (PMID 35190498, 2022). "Fibroblast growth factor-9 (fgf9) is one of the fibroblast growth factor, which plays an important role in the development of ovarian cancer, bone development, and gonadal differentiation." (PMID 36203875, 2022). "Through the evaluation of the two datasets downloaded from the GEO database, we found that FGF9 expressed more highly in normal ovarian tissues than ovarian cancer tissues (p < 0.0001)." (PMID 35190498, 2022). "Based on FGF9‐dependent control of metabolism, a role for FGF9 in cancer metabolism, specifically of ovarian cancer, has been hypothesized." (PMID 41131959, 2026). "In addition, fibroblast growth factor-9 (FGF-9) is secreted from ovarian cancer cells to induce M2 polarization of TAMs." (PMID 39802952, 2024). "Bioinformatics platforms that are employed to analyze the role of FGF9 in ovarian cancer." (PMID 35190498, 2022). "In ovarian cancer, circITGB6 directly interacted with IGF2BP2 and FGF9 mRNA, thereby stabilising FGF9 mRNA and inducing polarisation of TAMs towards M2 phenotype." (PMID 41399129, 2025). "Elevated levels of circITGB6 in cisplatin-resistant ovarian cancer cells form a complex with the RNA-binding protein IGF2BP2 and fibroblast growth factor 9 (FGF9) mRNA." (PMID 40330466, 2025). "In ovarian cancer, the study showed that circITGB6 can directly interact with IGF2BP2 and FGF9, thus stabilized FGF9 and promoted M2 polarization in ovarian cancer." (PMID 38637813, 2024). "In ovarian cancer, circITGB6 promotes an M2 macrophage‐dependent cisplatin resistance by forming a circITGB6/IGF2BP2/FGF9 RNA‐protein ternary complex by directly interacting with IGF2BP2 and FGF9 mRNA, which stabilize FGF9 mRNA and induce polarization of TAMs toward M2 phenotype." (PMID 39901896, 2025). "Multiple putative miRNA targets of NEAT1 and the downstream proteins have been proposed to contribute to the oncogenic roles of NEAT1 in ovarian cancer, such as the NEAT1/miR-1312/TJP3, NEAT1/miR-506, NEAT1/let-7 g/MEST/ATGL, NEAT1/miR‐382‐3p/ROCK1, and NEAT1/miR-365/FGF9 axes." (PMID 37986114, 2023).
non-small cell lung carcinoma (13 papers, 2013 to 2024). A group of at least three distinct histological types of lung cancer, including non-small cell squamous cell carcinoma, adenocarcinoma, and large cell carcinoma. "For example, FGF9 is highly expressed in the majority of non-small cell lung carcinoma (NSCLC) tumors, and its high expression is associated with a poor prognosis for NSCLC patients." (PMID 38962005, 2024). "Clinically, high expression of FGF9 is associated with poor prognosis in patients who have non-small cell lung cancer (NSCLC)." (PMID 33172093, 2020). "In addition, elevated FGF9 expression is associated with poor prognosis in non-small-cell lung cancer (NSCLC)." (PMID 38391921, 2024). "Previous studies showed that MiR-187 suppresses non-small-cell lung cancer cell proliferation by targeting FGF9." (PMID 35137650, 2022). "Furthermore, FGF9 expression has been observed in many non-small-cell lung carcinoma (NSCLC) primary tumors, and high expression of FGF9 is linked to the low survival rate of patients with NSCLC." (PMID 37108717, 2023). "FGF9 could act as a target gene of microRNA-219a-5p and relieved the chemoresistance of cisplatin in non-small cell lung cancer (NSCLC)." (PMID 35190498, 2022). "Interestingly, Fgf9 is expressed in 10% of human non-small cell lung carcinomas and induced expression of Fgf9 in adult mouse lung epithelium leads to the rapid formation of adenocarcinomas." (PMID 25978641, 2015). "In non-small cell lung cancer (NSCLC), FGF/FGFR pathway activation, mediated by FGF2 and FGF9 signalling through FGFR1 or FGFR2, has been suggested to promote EGFR inhibitor resistance." (PMID 37130917, 2023). "In human lung cancer, fibroblast growth factor 9 (FGF9), a high-affinity ligand for FGFR3, is overexpressed in 10% of primary resected non-small cell lung cancer (NSCLC) specimens." (PMID 27056048, 2016). "In human non-small-cell lung carcinomas (NSCLC), FGF2, FGF9, and their respective receptors, were also reported to mediate autocrine signaling which drives tumor resistance to specific kinase targeted therapy." (PMID 23900974, 2013).
colon carcinoma (11 papers, 2011 to 2023). "In our screen, we identified FGF9 as a gene implicated in the regulation of colon cancer cell adhesion." (PMID 21853123, 2011). "To date, limited information has been provided about the regulatory mechanism of FGF9 expression, such as prostaglandin E2 and hypoxia in endometriotic stromal cells and colon cancer cells, respectively." (PMID 31862949, 2019). "Collectively, these results demonstrated FGF9 commonly overexpressed in colon cancer cells and suggests FGF9-mediated signaling is an important mechanism in CRC tumorigenesis." (PMID 24334956, 2014). "In line, we found that expression of FGF9 in human colon cancer is correlated with patient's survival in the limited set of tumors that we examined." (PMID 21853123, 2011). "We found that FGF9 was expressed in colon cancer and expression levels correlate with patient survival, suggesting a functional role in the cancer." (PMID 21853123, 2011). "We found basal expression levels of FGF9 in the normal colon tissue profiles and in a majority of tumor profiles, but high expression of FGF9 in a subgroup of 7 colon tumors and 5 metastases (cut-off>2-fold compared to normal tissue)." (PMID 21853123, 2011). "Fibroblast growth factor 9 (FGF9) plays a critical role in patients with colon cancer with resistance to epidermal growth factor receptor (EGFR)-targeted therapy, and combination therapy with anti-EGFR inhibitor may reverse drug resistance." (PMID 36221049, 2022). "Upregulation of FGF9 in HCC may be caused also by hypoxia, e.g. in colon cancer cells, the FGF9 protein synthesis is repressed but switches to IRES‐dependent translation under hypoxic conditions." (PMID 32378800, 2020). "Although these genes are found to be overexpressed in several malignant tumours, including gastric and colon cancers, it remains unclear whether the products of FGF9, FLT1 and KLF5 are overexpressed in colorectal intramucosal adenocarcinoma." (PMID 28197804, 2017). "Finally, we provide evidence to show that hypoxia-induced translational activation promotes FGF9 protein expression in colon cancer cells." (PMID 24334956, 2014). "Although aberrant expression of FGF9 is known to promote cancer progression in many cancers including colon cancer, the mechanism of how FGF9 protein is elevated in cancer cells remains largely unknown." (PMID 24334956, 2014). "To demonstrate that elevation of FGF9 protein in colon cancer cells was due to hypoxia-mediated translational upregulation, we stained HIF-1α, a marker of hypoxic cells, in the same 40 pairs of samples and found that HIF-1α was upregulated in the colon cancer cells." (PMID 24334956, 2014). "Finally, we found that expression of FGF9 was strong in a subset of advanced colon cancers, and overexpression negatively correlated with patients' survival." (PMID 21853123, 2011). "Further studies are required to assess whether FGF9 could serve as a prognostic factor in colon carcinoma and whether gene expression programs activated by FGF9 are implicated in the regulation of tumor cell adhesion, motility and metastasis in intestinal cancer." (PMID 21853123, 2011). "In KRAS‐mutant pancreatic cancer cohort (n = 133), a strong correlation between PLK1 and FGF9, FGF14 was observed, and in KRAS‐mutant colon cancer (n = 170), only FGF14 strongly correlated with PLK1." (PMID 34369083, 2021). "Correlation analysis demonstrated that the levels of FGF9 were positively correlated with those of HIF-1α (R = 0.758, P < 0.0001), suggesting that aberrant expression of FGF9 in colon cancer cells is induced by hypoxia." (PMID 24334956, 2014). "Here, we identified a set of 21 genes, including FGF9, as determinants of tumor cell morphology by an RNA interference phenotypic screen in SW480 colon cancer cells." (PMID 21853123, 2011). "Furthermore, FGF9, a high-affinity ligand for FGFR3 is expressed in a large percentage of lung, prostate, and colon cancers." (PMID 27056048, 2016).
colon carcinoma (continued). "Our findings demonstrate a molecular mechanism that explains the aberrant expression of FGF9 protein, but not that of mRNA, in colon cancer cells." (PMID 24334956, 2014). "In another colon cancer cell line, HCT116, silencing of FGF9 had no apparent effect." (PMID 21853123, 2011).
glioma (11 papers, 2014 to 2022). A benign or malignant brain and spinal cord tumor that arises from glial cells (astrocytes, oligodendrocytes, ependymal cells). "Fibroblast growth factor 9 (FGF9), as an exosome-associated gene, was first found in human glioma cells, and it has been reported to participate in the regulation in glia of central nervous system." (PMID 35190498, 2022). "Fibroblast growth factor 9 (FGF9) known as one of 22 members of the fibroblast growth factors, was initially obtained from supernatant of a human glioma-derived cell lines and used to nourish primary rat glial cells." (PMID 33529250, 2021). "Fgf9 is first reported in a human glioma cell line and is a secreted polypeptide that is active in lung and bone development and steroidogenesis in postnatal Leydig cells." (PMID 31379938, 2019). "Fibroblast growth factor 9 (FGF9), also known as Glia-activating factor (GAF), was originally isolated from human glioma cells." (PMID 30157831, 2018). "FGF9 was first identified from the secretions of human glioma MCF-G1 cells, and found to promote NIH-3T3 cell line malignant transformation, suggesting that FGF9 may be a tumor-promoting factor." (PMID 34868990, 2021). "FGF9 is first identified from the secretions of human glioma MCF-G1 cells, and could promote NIH-3T3 cell line malignant transformation, suggesting that FGF9 may be a tumor-promoting factor." (PMID 32366371, 2020). "Fgf9 is a potent growth factor for glial cells and was originally isolated from a glioma cell line." (PMID 25978641, 2015). "Fibroblast growth factor 9 (FGF9) was first isolated from the culture supernatant of the human glioma cell line NMC-G1 and has been shown to participate in neuron development, bone formation, lens-fiber differentiation, gap-junction formation, sex determination, and steroidogenesis." (PMID 24603862, 2014).